POLGARF (POLG alternative reading frame)
Synonyms: ORF-Y
Gene: Protein-coding gene on chromosome 15 (89,330,208 to 89,333,809, reverse strand). Ensembl gene ENSG00000291307.
Subcellular location: Nucleus, nucleolus (POLG alternative reading frame); Secreted (POLGARF C-terminal fragment)
Gene Ontology:
Molecular function: protein binding
Cellular component: extracellular region; nucleolus